RN7SL399P (RNA, 7SL, cytoplasmic 399, pseudogene)
Gene: Miscellaneous RNA gene on chromosome 17 (41,730,127 to 41,730,405, reverse strand). Ensembl gene ENSG00000239542.
Homologues: Orthologues: chimpanzee Metazoa_SRP (99% identical), macaque Metazoa_SRP (89% identical). Paralogues in human: RN7SL143P (75% identical), RN7SL2 (75% identical), RN7SL398P (75% identical), RN7SL47P (75% identical), RN7SL1 (74% identical), RN7SL551P (73% identical), RN7SL567P (73% identical), RN7SL186P (73% identical), RN7SL386P (73% identical), RN7SL3 (72% identical), RN7SL45P (72% identical), RN7SL187P (72% identical), and 700 more.